CD4 (CD4 molecule)
Diseases named in the same sentence as CD4 in open-access papers (continued):
Sharing a sentence is not in itself a finding about the gene and the disease.
infection (continued). "As DC-SIGN+ cells are proposed to be the first host cells facilitating further infection of CD4+ T cells in trans, we investigated if LA could inhibit the transmission of the R5/X4 HIV-1 strain HE bound to DC-SIGN to the uninfected CD4+ target T cells." (PMID 26132818, 2015). "Alternatively, we hypothesized that Retnlb-/- mice might suffer an impaired ability to recruit CD4+ T cells to the colon upon infection, since an inability to recruit these cells could potentially explain their impaired IEC proliferation during infection." (PMID 26285214, 2015). "METH did not alter the expression of CD25 in CD4+ or CD8+ cells without infection as well (data not shown)." (PMID 26322025, 2015). "Initiation of antiretroviral therapy—a combination of drugs that keeps HIV replication in check but that does not cure the infection—is recommended when an individual’s CD4 count falls below 500 cells/μl or when he or she develops an AIDS-defining condition." (PMID 26348035, 2015). "The limitation of the study is related to the fact, that it was impossible to assess the time from infection to the care entry, therefore differences in HIV plasma viremia and CD4+ T cell counts related to the time of infection in association with investigated HLA variants were not analyzed." (PMID 26068923, 2015). "In FTOC, double positive CD4+CD8+ thymocytes were the principal target cells of infection and were progressively and severely depleted with no sign of apoptosis." (PMID 26175734, 2015). "Indeed, in an experimental infection of macaques by simian immunodeficiency virus (SIV), a rapid decrease of 90% of CD4+ T cells in the GALT was observed within 2 weeks of infection." (PMID 25759844, 2015). "Therefore, the expression of CXCR3 on splenic CD4+ and CD8+ T cells was examined on day 7 post-infection to determine if iron supplementation was attenuating T cell chemotaxis." (PMID 25768944, 2015). "Early treatment in this model (3 days after infection, i.e. post-exposure prophylaxis) leads to no decline in CD4+ T cell density, and no chronic infection phase." (PMID 25837979, 2015). "Infection with attenuated SIV causes dynamic and persisting changes to CD4 positive and CD4 negative lymphocyte populations in blood and lymphoid tissues." (PMID 25834093, 2015). "This is consistent with CD4+ T-cells (that express high amounts of CD4) being the major targets for infection by non-mac-tropic T/F viruses during transmission." (PMID 26055104, 2015). "We also used enhancement of infection by DEAE dextran and spinoculation to explore whether the different virus groups bound to CD4+ T-cells differently." (PMID 25809903, 2015). "For example, recently, it has been reported that in primary CD4+ T cells, HIV-1 reverse transcription is initiated approximately 3 h post-infection, its integration into the host DNA occurs around 8.5 h after infection, and that all viral transcripts have emerged by 15 h post-infection." (PMID 25996439, 2015). "Further support for LNs as a major site for continued infection of CD4 T cells was reported recently in non-human primates." (PMID 26623655, 2015). "Cell counting showed that the number of CD4+ and CD8+ T cells in the infection model group were lower than in the normal group (p < 0.05), and the middle- and high-dose FBTE groups exhibited enhanced numbers (p < 0.05) compared with the infection model group." (PMID 26140539, 2015). "The conserved HIV-1 Vpr protein has been previously shown to promote T cell infection and disease progression in an animal model; however, infection of primary CD4+ T cells in culture does not require Vpr, and its mechanism of action remains undefined." (PMID 26186441, 2015). "Many authors have shown that CD4+ T cell help-independent CD8+ T cell responses are essential for the early control of primary ECTV infection, while CD4+ T cell help-dependent Ab responses are essential for the late infection clearance." (PMID 25873756, 2015).
infection (continued). "We hypothesize that co-infection with HIV-1 will affect HBV detection in CD4+/CD8+ T cells, CD14+ monocytes, CD19+ B and/or CD56+ NK cells as compared to HBV mono-infection." (PMID 26390290, 2015). "Higher HIV viral loads have been associated to poor neuropsychological function among children and adolescents, while CD4+ and CD8+ T-cells are fundamental for HIV infection control, with their efficiency fluctuating from time of infection and specific type of surface receptors." (PMID 28596857, 2015). "The T cell surface antigen CD4 has been shown to homo dimerise through an allosteric disulfide bond in domain 2, which alters its function from a co stimulatory molecule to a receptor involved in HIV viral fusion and infection." (PMID 26379032, 2015). "HIV-1 entry into CD4+ cells is mediated by co-receptors CCR5 (R5 viruses) and CXCR4 (X4 viruses), and CCR5 is dominant over CXCR4 in HIV transmission from person to person and early in infection." (PMID 26172445, 2015). "On day 18 after infection there was no change in the number of CD4+ cells, however a slight increase of CD8+ and double positive was observed in the IP infected animals compared to the control." (PMID 26469517, 2015). "There was no increase in the percentage of CD4+ Foxp3+ Treg cells expressing IL-10 upon infection in either the tLN or spleen." (PMID 26195548, 2015). "In a nine-day infection of primary chimpanzee CD4+ T cells, we did not observe any signature of APOBEC3D deaminase activity in the presence of SIVsmm Vif." (PMID 26394054, 2015). "On the other hand, wt RABV (DRV-NG11) infection did not induce activation of immune cells, rather it reduced the number of activated DCs, B cells, and CD4 T cells." (PMID 26292099, 2015). "Similar to TNF-alpha expression by CD4+ T cells after 72 hours, infection with either strain did not induce an increase expression of granzyme A." (PMID 26147698, 2015). "The infection with either strain did not alter the percentage of expression of IL-10 by CD4+ T lymphocytes." (PMID 26147698, 2015). "We conclude that non-macrophage-tropism of HIV-1 R5 Envs in vitro is determined predominantly by a reduced capacity to target myeloid cells via low CD4 rather than a specific adaptation for T-cells entry that precludes macrophage infection." (PMID 25809903, 2015). "Although γδ T cells represent only a small fraction of the total CD3+ T lymphocytes, frequency of infection within isolated Vδ2 cells was not statistically different from that in r-CD4 cells." (PMID 26473478, 2015). "Neither do CD4 or CCR5 levels explain the low overall infection levels observed for Jurkat/CCR5 and primary CD4+ T-cells." (PMID 25809903, 2015). "Firstly, we examined whether virus-specific CD4+ T cell responses were also diminished in the lung draining LNs (mediastinal LNS, MedLN) and at the site of infection in mice prophylactically-treated with oseltamivir as compared to controls." (PMID 26086392, 2015). "Despite productive infection of alveolar macrophages, macrophage populations were preserved, but CD4+ T cell populations were depleted even though they were not productively infected." (PMID 25933119, 2015). "We concluded that the CD4+CD25+ cells in the thymus and spleen migrated out to the periphery following IBDV infection to effect their immunosuppressive role during the early stages of infection." (PMID 25803101, 2015). "Nevertheless, in a study where human volunteers were infected over time with several low doses of Plasmodium iRBCs and treated to clear the infection, protection from a challenge infection was positively correlated with numbers of circulating IFN-γ-producing CD4+ T cells." (PMID 26426121, 2015). "The principal age-related changes observed, independent of infection status, concerned decreases in the frequencies of CD4+, NKdim and NKT cells, whilst CD8+, Treg and Teff cells' frequencies increased from birth to 12 months of age." (PMID 26580401, 2015).
infection (continued). "Intriguingly, double infection did not occur stochastically across all CD4+ T cells maturation subsets but rather occurred preferentially in central memory (TCM) cells." (PMID 26559763, 2015). "Although CD4+ T lymphocytes are the most abundant HIV-1-infected cell type in vivo and are responsible for much of its pathogenesis, T lymphocytes are relatively refractory to infection by cell-free HIV-1 in vitro." (PMID 26186441, 2015). "In contrast, IFN-γ expression, a cytokine mainly produced by NK cells and activated CD4+ and CD8+ T cells that promotes cell-mediated immune responses to intracellular pathogens, was maximal at day 8 post-infection at a time when peak lymphocyte lung infiltration was noted." (PMID 26641081, 2015). "Non-macrophage-tropic R5 Envs require high levels of CD4 for infection contrasting with macrophage-tropic Envs, which can efficiently mediate infection of cells via low CD4." (PMID 26055104, 2015). "In addition, the aerosol boosting using γ-irradiated BCG three times successively induced antigen-specific CD4+ T cells that were IFN-γ+TNF-α+IL-2+, which were maintained until at least 10 weeks post-infection." (PMID 26509812, 2015). "Our results demonstrate that T/F, early or late disease non-mac-tropic R5 Envs do not preferentially mediate infection of primary CD4+ T-cells compared to highly mac-tropic Envs from brain tissue." (PMID 25809903, 2015). "Blockade of CD4 before spinoculation inhibited upregulation of CTLA-4 and GITR during infection." (PMID 26482032, 2015). "Infection also failed to stimulate the production of IL-10 by Foxp3+ Treg cells, despite increased IL-10 production by CD4+ Foxp3− IL-4+ Th2 cells." (PMID 26195548, 2015). "Despite the predominance of infection in macrophages, CD4+ T cells, but not macrophages were depleted in lungs." (PMID 25933119, 2015). "Changing the CD4 count decline resulted in very slight changes in the treatment rate and in no changes in the infection rate." (PMID 26091253, 2015). "By day 6 post infection, CD8 and CD4 T cells seemed to become the dominant IFNγ producing cells." (PMID 26070118, 2015). "As expected, in the presence of AZT no HIV-1 infected cells were found when uninfected, resting CD4+ T lymphocytes were used as target cells, thus excluding events of productive infection due to transmission of HIV-1 from productively infected cells." (PMID 26502902, 2015). "Recipients of WT CD4 T cells showed a significant reduction in the numbers of adult worms recovered from the small intestine at day 5 post infection, whereas recipients of M3R−/− CD4 T cells showed no reduction in worm burden." (PMID 25629518, 2015). "Percent CD4+ T cell count has substantially less variability than absolute CD4+ number and although essential for monitoring pediatric infection, it is not widely available in developing countries." (PMID 26110761, 2015). "In a more recent study, we have shown increased expansion of Treg cells in dectin-/- mice infected with P. brasiliensis, which paralleled a diminished activation and migration of CD4+ and CD8+ T cells to the site of infection, resulting in a more severe disease outcome." (PMID 26512987, 2015). "Consistent with our expectations, a large fraction of the total CD4+ T cells in the LI LP expressed classical markers of inflammatory Th1 cells; the cytokine IFN-γ and the transcriptional regulator T-bet after infection." (PMID 25942314, 2015). "We investigated T-cell tropism of non-mac-tropic R5 Envs that require high levels of CD4 for infection including several T/F and acute stage Envs and compared to highly mac-tropic variants mostly derived from brain tissue." (PMID 25809903, 2015). "In section 3.6, SRLVs do not replicate productively in T lymphocytes and both in early and late phases of infection there is no measurable depletion of CD4+ T lymphocytes in the periphery; therefore, infected animals do not undergo immunodeficiency." (PMID 29061947, 2015).
infection (continued). "Untreated CD4+ T cells from peripheral blood, which expressed no activation markers, produced very little productive infection (0.47%)." (PMID 26067822, 2015). "Surprisingly, we found that the Gag+ cells expressed surface CD3 but were negative for CD4 after direct infection." (PMID 26537682, 2015). "Only by day 6 post infection, do CD8 and CD4 T cells become the dominant IFNγ sources." (PMID 26070118, 2015). "Although the highest absolute number of single IFN-γ+ CD4+ T cell responses to PPD or A1D4 was conferred by A1D4/MTO-immunized mice, it did not positively correlate with the strongest protection against infection among all the groups, which supports the previous conclusion." (PMID 25822536, 2015). "In support of this, Zhao and coworkers found that high levels of peripheral CD4+ T-cells against internal viral proteins in the early phase of infection, rather than low levels of CD8+ cells T-cells, correlated with disease severity during the 2009 pandemic." (PMID 26606759, 2015). "Although dermal CD4+ T cells from 1x pinnae recovered on day 1 after infection did not proliferate in response to SSAP, a proportion of them were positive for IL-10 compared to naive mice." (PMID 25974019, 2015). "Duration of suppression was significantly and inversely related to baseline plasma viral load, but not to sex, duration of infection (acute vs. early), injection drug use, route of infection, age, or baseline CD4 cell count (data not shown)." (PMID 26600459, 2015). "Conversely, JRCSFNefdd infected BLT mice showed no reduction in peripheral blood CD4+ T cells which is similar to what was previously observed during the course of LAINefdd infection under similar experimental conditions." (PMID 26169178, 2015). "The CD4 count at draw, CD4 nadir, infection duration, and VACS index were not significantly different between IP+ and IP- HIVpos subjects." (PMID 24819230, 2014). "The HCV NS3 is considered to be an important target for development of HCV therapeutic vaccines because NS3-specific CD4+ and CD8+ T cell responses correlate well with resolution of the infection and have been described as an indicator for viral clearance both in humans and chimpanzees." (PMID 24901478, 2014). "We also demonstrate that HIV-1 can be subsequently released and transmitted to CD4+ T-cells without de novo synthesis, suggesting astrocytes support trans-infection." (PMID 24587404, 2014). "Cd28flox/floxOx40cre/+ mice had comparable levels of Influenza M1 viral RNA in their lungs compared with heterozygous control mice at 7 days post infection, suggesting that the loss of CD28 on effector CD4+ T cells does not impair viral clearance." (PMID 25347065, 2014). "Seven patients had no infection and 14 had a controlled infection, while both groups maintained CD4+ T-cell numbers above the established cut-off (0.4 cell/μL blood)." (PMID 25166270, 2014). "During infection with HIV-1, the virus primarily infects and replicates in activated CD4+ T cells." (PMID 24886416, 2014). "Mean blood CD4+ T cell levels were significantly suppressed in FIV [+] animals at weeks 8 and 12 post-infection compared to FIV [-] animals (p < 0.001) and mean blood CD8+ T cell levels were elevated in FIV [+] animals at week 8 post-infection (p < 0.01)." (PMID 24886384, 2014). "After infection, they upregulated HLA-DR and CD40, which are required for CD4+ T cell priming." (PMID 25071784, 2014). "Likewise, the proportion of CD4+ cells that individually express IFN-γ, TNF-α and IL-2 remained high eight-weeks post infection." (PMID 25500571, 2014). "As seen in the experiments with T cells from healthy control individuals, memory CD4+ T cells from patients with CF produce significant amounts of IL-17A, IL-22 and IFN-γ in response to DC infection with either laboratory or clinical PA strains compared with uninfected DCs." (PMID 24587305, 2014).
infection (continued). "Although DCs bind and shuttle HIV to CD4+ T cells for infection, HIV does not efficiently replicate in monocytes and DCs." (PMID 25474197, 2014). "This decrease may have been due, at least in part, to infection with PPRV, as the proportion of CD4+ cells staining for intracellular H was greater than that of CD8+ cells, 4 days after PPRV challenge." (PMID 24568545, 2014). "However, 12 days post infection, Cd28flox/floxOx40cre/+ mice had reduced numbers of CXCR5+Bcl-6+CD4+ Tfh cells and IFNγ+CD44highCD4+ Th1 cells in the medLN and Th1 cells in the lungs compared to control mice." (PMID 25347065, 2014). "Together, these data suggest that cellular interactions between CD4+ T cells expressing CD28 and CD19+B220+ B cells are required for the expansion and/or recruitment of follicular B cells into the lymphoid tissue during N. brasiliensis secondary infection." (PMID 24516382, 2014). "Seven days post primo-infection of the re-infection group, the infected animals had a significantly lower mean percentage of CD4+ T cells than the non-infected animals." (PMID 25252649, 2014). "This can be appreciated by comparing the CD4/CCR5 expression level combinations that give rise to low levels of infection (green areas), or conversely, those that give rise to the highest level of infection (red areas), between the wt and mutant Envs." (PMID 24957778, 2014). "CD4+ and CD8+ T cells are critical for controlling many infections." (PMID 24722202, 2014). "Both CD4+ and CD8+ T-cell responses play essential roles in the outcome of infection." (PMID 25426115, 2014). "Consistent with our previous observations 7 days after infection with C. albicans, absolute numbers of CD4+ T-cells were augmented in the CLNs of non-Tg, but not of Tg mice, at this time point." (PMID 25344377, 2014). "In general, all strains demonstrated an IFN-γ response by CD4+CD44+ and CD8+CD44+ cells to the crude M. leprae antigens (membrane, CWA, cytosol) and to ML2028 (Ag85B) at one or more points during long-term infection." (PMID 25210773, 2014). "Although only a small number of 2W1S:I-Ab+CD4+ T cells were detectable 2 days post-infection (dpi) with Lm-2W, these lacked expression of OX40." (PMID 24771127, 2014). "Using adoptive transfer of T cells from healed mice into naïve congenic recipients, we also demonstrated that this differential activation of CD4+ and CD8+ T cells by high and low dose infections, respectively, is observed in vivo following L. major challenge." (PMID 25412267, 2014). "After the initial infection, CMV may persist in a state of latency; effective control of the virus is dependent on an intact CD4+ and CD8+ cell mediated immunity." (PMID 25399401, 2014). "As infection progresses, presumably the ILC2 response increases, but this occurs alongside initiation of the adaptive arm of the response with production of antigen-specific CD4+ T cells." (PMID 24942690, 2014). "We only observed an increase in glycolytic flux in primary CD4+ T cells after infection with HIV-1 but not in the T cell lines Jurkat and CEM-ss." (PMID 25421745, 2014). "Based upon our work and work from others, we hypothesized that activated TGFβ+GARP+ Treg cells from FIV+ cats were capable of converting CD4+ Th cells to Treg cells, thereby maintaining Treg cells numbers and function during the course of FIV infection." (PMID 24438223, 2014). "Although the overall frequency of T cells in the blood did not change during infection, there was a dramatic reduction in αCD3 responses of both CD4+ and CD8+ T cells from WT-infected RM at 7–21 dpi." (PMID 24832205, 2014).